NNMT (nicotinamide N-methyltransferase)
Diseases named in the same sentence as NNMT in open-access papers (continued):
Sharing a sentence is not in itself a finding about the gene and the disease.
benign prostate hyperplasia (1 paper, 2014). "Immunohistochemical NNMT expression was examined in 26 cases of benign prostate hyperplasia (BPH), 18 cases of high-grade prostatic intraepithelial neoplasia (HGPIN) and 120 cases of PCa." (PMID 25120681, 2014).
bipolar disorder (1 paper, 2020). A disorder of the brain that causes unusual shifts in mood, energy, activity levels and the ability to carry out day-to-day tasks. "Bipolar disorder (BD) is associated with metabolic abnormalities and NNMT regulates energy metabolism and may also exert a causal role in metabolic disorders." (PMID 32000734, 2020).
cervical cancer (1 paper, 2024). A primary or metastatic malignant neoplasm involving the cervix. "Our investigation into C1 NNMT+ CAEPCs was motivated by the relatively unexplored role of NNMT in cervical cancer." (PMID 39840054, 2024). "Moreover, the tissue origins of the five cervical cancer CAEPCs subpopulations were examined, showing that C2 PSORS1C2+ CAEPCs primarily originated from H2 and T4, whereas C1 NNMT+ CAEPCs mainly derived from T1." (PMID 39840054, 2024).
cystitis (1 paper, 2023). Inflammation of the urinary bladder. "First, validation of NNMT, GALK1, and HTRA1 and other candidates tightly correlated with BCa stage needs to be performed using larger patient cohorts of BCa including benign conditions such as cystitis, samples with hematuria, as well as other tumors from the urogenital tract (prostate, and renal)." (PMID 37834386, 2023).
endometriosis (1 paper, 2024). The growth of functional endometrial tissue in anatomic sites outside the uterine body. "In this study, we found that aberrantly high expression of NNMT is associated with the proliferation, migration and invasion of ESCs, contributing to the progression of endometriosis." (PMID 39489776, 2024). "Investigating the mechanisms underlying NNMT upregulation in eESCs, we considered the hormonal context of endometriosis." (PMID 39489776, 2024). "This overexpression rescued the impaired proliferation caused by NNMT knockdown, providing novel insights into the pathogenesis of endometriosis." (PMID 39489776, 2024). "By analyzing datasets GSE5108, GSE7305, GSE141549, GSE23339, and GSE25628, we identified a significant overexpression of NNMT in the eutopic endometrium and ectopic lesions of endometriosis patients compared to normal endometrium." (PMID 39489776, 2024). "The exact mechanisms through which macrophages induce NNMT expression in ESCs and the role of NNMT in endometriosis-related macrophage function are compelling subjects for future investigation." (PMID 39489776, 2024). "To elucidate the role of NNMT in endometriosis, we initially explored its expression in endometrium and various types of endometriotic tissue using the Turku Endometriosis Database (GSE141549)." (PMID 39489776, 2024). "Our findings indicate that JBSNF-00008 significantly alleviated the progression of endometriosis in vivo, suggesting that NNMT is a promising therapeutic target." (PMID 39489776, 2024). "Detailed characterizations of NNMT could pave the way for the development of new inhibitors for treating endometriosis." (PMID 39489776, 2024). "Altogether, these results indicate that the overexpression of NNMT induced by estrogen and macrophage interaction modulates ESC proliferation via the NNMT-ERBB4-PI3K/AKT signaling pathway, as well as promotes cellular migration and invasion, contributing to the development of endometriosis." (PMID 39489776, 2024).
gastric cardia adenocarcinoma (1 paper, 2025). A carcinoma that arises from glandular epithelial cells of the cardia of stomach. "Results from gastric cardia adenocarcinoma indicate that nicotinamide N-methyltransferase (NNMT) is enriched in AQP5 expressing stem cells and that their stemness is maintained by NNMT-mediated nicotinamide metabolism, which causes reduction of H3K27 trimethylation and activation of WNT signaling." (PMID 40102611, 2025).
gastric cardia carcinoma (1 paper, 2025). A carcinoma that arises from epithelial cells of the cardia of stomach. "For instance, CD24+CD44+EpCAM+ gastric CSCs are significantly associated with poor patient prognosis, and the NNMT+/AQP5+ phenotype could serve as a potential diagnostic marker for gastric cardia cancer." (PMID 40665579, 2025).
Graves disease (1 paper, 2025). Graves' disease is an autoimmune disorder that leads to overactivity of the thyroid gland (hyperthyroidism).It is caused by an abnormal immune system response that causes the thyroid gland to produce too much thyroid hormones. "One study found that NNMT expression was increased in the thyroid glands of patients with Graves’ disease." (PMID 39807704, 2025).
head and neck cancer (1 paper, 2017). A primary or metastatic malignant neoplasm affecting the head and neck. "Remarkably, in a very recent report, the overexpression of NNMT was found in cancer stem cells (CSCs)-enriched subpopulation in head and neck cancer." (PMID 28286742, 2017).
heart failure (1 paper, 2024). Inability of the heart to pump blood at an adequate rate to meet tissue metabolic requirements. "In contrast to heart failure from other causes, this NAD+ deficiency is due to induction of NNMT by SQSTM1-NF-κB signaling." (PMID 38212381, 2024).
hepatoblastoma (1 paper, 2017). Hepatoblastoma (HB) is a malignant hepatic tumor and is the most common pediatric liver cancer. "Therefore, we speculate that NNMT dysregulation caused by epigenetic changes may be a suitable mechanism linked to the origin of hepatoblastomas, thus deserving further investigation." (PMID 29228658, 2017). "Three genes identified in our hepatoblastoma analyses were also listed in the top 20 differentially methylated genes during liver development: CRP, NNMT (both hypermethylated) and C3P1 (hypomethylated)." (PMID 29228658, 2017).
hyperhomocysteinemia (1 paper, 2023). A serious metabolic condition caused by mutations in the MTHFR gene, medications, or nutritional deficiency. "The A/G polymorphism NNMT (rs694539) is also known to be associated with hyperhomocysteinemia." (PMID 37273715, 2023).
hypertensive nephropathy (1 paper, 2023). Kidney damage that results from chronically elevated blood pressure; complications include glomerular damage resulting in proteinuria and hematuria. "A recent bioinformatics study on the GSE37455 dataset identified three core ferroptosis-related genes, namely, albumin (ALB), nicotinamide N-methyltransferase (NNMT), and ATF3, that were differentially expressed in hypertensive nephropathy samples compared with normal samples." (PMID 37739961, 2023).
mesenchymal tumors (1 paper, 2024). "The consequences of NNMT overexpression, such as the activation and inactivation of oncoproteins and tumor suppressor proteins, respectively, as well as the enrichment of the cancer stem cell population overlap with the major mechanisms responsible for poor prognosis in mesenchymal tumors." (PMID 39295619, 2024).
migraine (1 paper, 2016). "After stratification, we were able only to show an association between the NNMT gene rs694539 variant and female patients with migraine on the genotype and allelic levels." (PMID 27726107, 2016). "Here we report the association of the Nicotinamide-N-methyltransferase gene (NNMT) rs694539 variant with migraine in a case–control study of 433 patients with migraine and 229 healthy controls (χ2 = 6.076, P = 0.048)." (PMID 27726107, 2016). "To do so we analyzed the allele and genotype frequencies of the NNMT gene rs694539 variant in 433 patients with migraine and 229 healthy controls." (PMID 27726107, 2016). "With the polymerase chain reaction-restriction fragment length polymorphism method developed recently in our laboratory, we were able to show an association between the NNMT gene rs694539 variant and migraine for the first time." (PMID 27726107, 2016). "Consequently our results clearly indicate that the NNMT gene rs694539 variant is a genetic risk factor for migraine." (PMID 27726107, 2016). "In summary, the role of the rs694539 variant of the NNMT gene in migraine is unclear." (PMID 27726107, 2016). "Thus, our findings suggest that the rs694539 variant of NNMT gene may play a role in the etiopathology of migraine in the Turkish population studied herein." (PMID 27726107, 2016). "We also wanted to reveal whether the rs694539 variant of NNMT gene is associated with migraine." (PMID 27726107, 2016).
renal failure (1 paper, 2022). "Besides, the results from mice experiments indicated that the increase in plasma N-Me-2PY and N-Me-4PY levels during renal failure did not correlate with a decrease in clearance; rather, it was influenced by NNMT." (PMID 35430611, 2022).
urogenital cancers (1 paper, 2025). "Nicotinamide N-methyltransferase (NNMT), as a key enzyme in the nicotinamide metabolic pathway, shows high expression heterogeneity in different tumors, especially in most gastrointestinal and urogenital cancers." (PMID 41226585, 2025).
cancer (163 papers, 2009 to 2026). A tumor composed of atypical neoplastic, often pleomorphic cells that invade other tissues. "For example, the cancer-associated fibroblast regulator NNMT, CD163, a marker of tumor-associated macrophages (TAMs), and oncogenic proteoglycan VCAN were significantly upregulated from the NFT stroma to the invasive stroma." (PMID 41233595, 2026). "Recently, NNMT has a role in methylation metabolism and tumorigenesis and was associated with a poor prognosis against numerous cancers." (PMID 40853419, 2025). "NNMT is mainly expressed in the liver and white adipose tissue but is also upregulated in tumor cells and cancer-associated fibroblasts (CAFs)." (PMID 40864763, 2025). "The second phase represented GSTP1 (encodes glutathione S-transferase π) and NNMT (encodes nicotinamide N-methyl transferase) expression, which increased in all stages of cancer development." (PMID 41465541, 2025). "NNMT, involved in the methylation of nicotinamide and other pyridines, has been linked to cancer cell metabolism, growth, and metastasis." (PMID 39035994, 2024). "We examined the associations between NNMT expression and the activities of various clinical chemotherapies in cancer patient cohorts." (PMID 38809277, 2024). "Further research is warranted to elucidate the precise mechanisms underlying NNMT dysregulation in cancer and to explore its therapeutic implications fully." (PMID 38809277, 2024). "The knockdown of NNMT in cancer-associated fibroblasts (CAFs) resulted in an increase in the NAD+ levels." (PMID 38921477, 2024). "Combining bioinformatics analysis and experimental validation, we have demonstrated that NNMT is overexpressed in multiple cancer types and is associated with poor prognosis." (PMID 38809277, 2024). "NNMT has been found to be upregulated in multiple cancer cell types, causing a decrease in the SAM:SAH ratio through consumption of SAM, ultimately leading to an altered epigenetic state." (PMID 39272943, 2024). "Previous studies have identified NNMT as a key metabolic regulator in the differentiation of cancer-associated fibroblasts (CAFs) in the tumor stroma, emphasizing its therapeutic potential and its crucial role in cancer progression." (PMID 39840054, 2024). "Paradoxically, NNMT activity is associated with cell migration, invasion, and chemoresistance in cancer cells." (PMID 39489776, 2024). "Within these tumor types, NNMT has been implicated in enhancing the migratory, invasive, proliferative, and survival capabilities of cancer cells." (PMID 38921477, 2024). "Evidence indicates that NNMT overexpression is associated with an increase in cancer cell survival, proliferation, migration, and invasion." (PMID 38921477, 2024). "We further found that NNMT expression in different pathological stages of cancers was significantly different, consistent with the previous study showing that increased expression of NNMT was associated with increased tumor stage in STAD and OV." (PMID 36817086, 2023). "Cancer resistance to 5-FU is often characterised by the upregulation of nicotinamide N-methyltransferase (NNMT), which is associated with increased aggressiveness." (PMID 37628772, 2023). "NNMT has been reported to be overexpressed in several tumors, and its upregulation has been linked to cancer cell invasion and migration." (PMID 37834411, 2023). "Owing to this role, NNMT is an established cancer-associated metabolic enzyme and its overexpression has been implicated in tumor progression, metastasis, and poor clinical prognosis." (PMID 36672415, 2023). "NNMT (nicotinamide N-methyltransferase) plays a vital role in cancer-associated fibroblasts, involving depletion of S-adenosyl methionine and reduction in histone methylation." (PMID 37501723, 2023). "We focused on nicotinamide N-methyltransferase (NNMT), which is a cytosolic enzyme that has been identified as a significant metabolic regulator of cancer-associated fibroblasts." (PMID 37719863, 2023).
cancer (continued). "Dysregulation of NNMT activity has been associated with numerous conditions, including diabetes mellitus, liver disease, neurodegenerative disorders, and cancer." (PMID 36143291, 2022). "Evidence accumulates that NNMT mRNA and protein levels are elevated in various human cancers, and enhanced NNMT expression has been associated with tumor progression." (PMID 35338115, 2022). "NNMT was also shown to regulate histone methylation in cancer‐associated fibroblasts, supporting oncogenic remodelling of the metastasis‐associated stroma." (PMID 35678045, 2022). "The study of NNMT as a metabolic regulator of cancer-associated fibroblasts is particularly important." (PMID 35884600, 2022). "Given its roles in drug metabolism, epigenetic regulation, and pan-cancer stromal expression, NNMT has the potential to serve as a screening marker for early detection and risk stratification for guiding therapeutic cancer management." (PMID 35177765, 2022). "As a cancer stromal protein with important roles in metabolism and cancer epigenetics, NNMT is emerging as a promising biomarker for risk stratification of early-stage cancers." (PMID 35177765, 2022). "In cancer-associated fibroblasts (CAFs), the expression of NNMT was associated with depletion of SAM and a reduction in histone methylation, resulting in alterations in gene expression." (PMID 36186458, 2022). "In the majority of cancer types, NNMT methylation was found to be closely associated with NNMT mRNA expression." (PMID 36386816, 2022). "Our findings, based on the existing evidence, showed that high NNMT expression was associated with worse prognosis of cancer patients, and our findings were further confirmed by the TCGA data." (PMID 35233465, 2022). "The overexpression of NNMT is associated with the enhanced proliferation, invasion, and metastasis of various cancers." (PMID 35222522, 2021). "Significant NNMT upregulation was recently found in epithelial neoplasms and in association with cancer stem cells (CSCs)." (PMID 34439880, 2021). "These cells showed moderate morphological differentiation as well as several changes in cancer-associated genes, including NNMT." (PMID 34827592, 2021). "NNMT, which is a major metabolic regulator, is dysregulated and associated with a worse prognosis in various cancers, including GC." (PMID 34252149, 2021). "NNMT is also highly expressed in metastasis-associated cancer-associated fibroblasts (CAFs) in the context of ovarian cancer." (PMID 34109280, 2021). "This process is supported by recent proteomics-based studies revealing NNMT to be the master regulator of the differentiation of cancer-associated fibroblasts (CAFs)." (PMID 34572571, 2021). "Nicotinamide N-methyltransferase (NNMT) in the stroma was found to be the key molecule regulating HGSC metastasis by mediating the differentiation of cancer-associated fibroblasts (CAF)." (PMID 34063807, 2021). "Here we describe the synthesis of pillar[n]arenes to target 1-methylnicotinamide (1-MNA), which is one metabolite of vitamin B3 (nicotinamide) produced by the cancer-associated nicotinamide N-methyltransferase (NNMT)." (PMID 36703437, 2020). "Nicotinamide N-methyltransferase (NNMT) is a metabolic regulator of cancer-associated fibroblast (CAF) differentiation and cancer progression." (PMID 33193702, 2020). "Scleric acid was shown to exhibit moderate inhibition activity against Mycobacterium tuberculosis, as well as inhibition of the cancer-associated metabolic enzyme nicotinamide N-methyltransferase (NNMT)." (PMID 30746093, 2019). "NNMT is implicated in various disease conditions such as metabolic disorders, neurodegenerative diseases and cancer, and tissue NNMT expression or plasma levels of its product MNA have been proposed as biomarkers for these conditions." (PMID 29483571, 2018).